CASP8 (caspase 8)
Diseases named in the same sentence as CASP8 in open-access papers (continued):
Sharing a sentence is not in itself a finding about the gene and the disease.
colon carcinoma (continued). "Therefore, it is hypothesized that the caspase-8-mediated external pathway is more important in colon cancer cells; therefore, we speculated whether the same phenomenon is observed in other tumor cells, indicating that the death receptor is an important mechanism for anoikis." (PMID 37667281, 2023). "The type of cell death is presumably oxeiptosis led by ROS in colon cancer, as C-PARP, caspase-3, caspase-8, and c-caspase-8 levels are steady or slightly decreased." (PMID 35884370, 2022). "Experiments using multidrug treatment of colon cancer cells indicated that AMPK activation promoted apoptosis by phosphorylating Beclin-1 at Ser93/96, which increases Beclin-1 cleavage by caspase-8." (PMID 35054445, 2021). "Cleavage of caspase-3, including cleaved caspase-3, caspase-8, including cleaved caspase-8, and caspase-9, including cleaved caspase-9, was seen in HCT-116 and HT-29 colon cancer cells." (PMID 34834153, 2021). "We observed decreased levels of pro-caspase 3, pro-caspase 8, and full-length-PARP, demonstrating the induction of apoptosis by Tet in colon cancer cells." (PMID 31040202, 2019). "Output data from this study showed BJEE inhibited the cell proliferation of HCT-116 colon cancer cells at IC50 value of 8.9 ± 1.32 (μg mL−1) and significantly increased the levels of caspase-8, 9, and 3/7 in treated cells in comparison to untreated." (PMID 35538944, 2018). "MMPP (0-15 μg/mL) enhanced the expression of apoptotic proteins such as Bax, cleaved caspase-3 and cleaved caspase-8 while decreased the expression of anti-apoptotic protein Bcl-2 in HCT116 and SW480 colon cancer cells." (PMID 29207641, 2017). "Markedly increased protein levels of cleaved caspase-8 and caspase-9 were detected in TSLP-treated colon cancer cells, suggesting the involvement of both pathways." (PMID 26919238, 2016). "Apigenin augments TRAIL-induced apoptosis in Jurkat leukemia cells, DU145 prostate cancer cells, and DLD-1 colon cancer cells through upregulation of TRAIL-R2 and activation of Bid and caspase-8, -10, -9, -3." (PMID 24324518, 2013). "Apigenin augments TRAIL-induced apoptosis in Jurkat leukemia T cells, DU145 prostate cancer cells, and DLD-1 colon cancer cells through upregulation of TRAIL-R2, activation of Bid and caspase-8, -10, -9, -3." (PMID 23573148, 2013). "This may indicate that D. maritima bulb extract induces apoptosis in colon cancer cells through the TNF-α, IL-6, and caspase-8 activation pathways." (PMID 36770882, 2023). "Studies have shown that inhibition of caspase-8 can increase anoikis resistance in colon cancer cells; however, inhibition of caspase-9 activity does not achieve the same results." (PMID 37667281, 2023). "We report that downregulation of cFLIP proteins levels is an early event upon treatment of 2D cultures of colon cancer cells with ER stress inducers, preceding TNF-related apoptosis-inducing ligand receptor 2 (TRAIL-R2) upregulation, caspase-8 activation, and apoptosis." (PMID 35115486, 2022). "Moreover, GEN and DAI induce caspase-8 expression and inhibit PI3K activity, which results in an increased level of FOXO3.All these functions lead to a final apoptosis of colon cancer cells." (PMID 29849534, 2018). "We stained paraffin sections from colon cancer biopsies of three individuals with antibodies against Aconitase 2 as a reporter of mitochondrial mass and, simultaneously, against one of the proteins Bax, Bcl-2, Bid, Mcl-1, Smac, XIAP, Casp8 and Bar." (PMID 29374163, 2018).
colon carcinoma (continued). "Recently, Panaretakis found that anthracycline drugs mitoxantrone and oxaliplatin can stimulate ER stress in colon cancer cell line CT26, activate the phosphorylation kinase of ER elF2α, resulting in the phosphorylation of elF2α and structural changes of caspase-8, apoptosis regulators BAX and Bak." (PMID 28938593, 2017). "Indeed, increased expression of both caspase-9 and caspase-8 was reported in EPA- and DHA- induced apoptosis in human HL-60 leukemia and Caco-2 colon cancer cells, respectively." (PMID 26821053, 2016). "Our work demonstrates that caspase-3 loss sensitizes colon cancer cells to genotoxic agents by promoting RIP1-, pro-caspase-8-, and ROS-dependent necrosis, without blocking apoptosis." (PMID 25906152, 2015). "Caspase-3 knockout (C3KO) or knockdown (KD) colon cancer cells showed normal apoptotic response, but increased sensitivities to DNA-damaging agents in cell culture and in mice, at least in part, via RIP1-, and caspase-8-dependent necrosis." (PMID 25906152, 2015). "Apoptosis induced by CPDD, VP16 and vinblastine (VB) was shown involve Fas receptor clustering and Caspase 8 activation and was independent of Fas ligand in various colon cancer cells and leukaemia cells." (PMID 12402161, 2002). "Research on colon cancer has shown that the level of TIPE2 in colon cancer tissues is significantly upregulated compared to adjacent normal tissues and that TIPE2 participates in the development of colon cancer by binding caspase 8, thereby inhibiting the TLR4 inflammatory pathway." (PMID 33850476, 2021). "Numerous other molecular mechanisms were suggested for the pro-apoptotic effect of SF, such as the cleavage of caspase-8 in pancreatic cancer, the fragmentation of the DNA-repairing protein poly (ADP-ribose) polymerase (PARP) and decreased expression of BCL2 in mammary, prostate and colon cancers." (PMID 32773768, 2020). "Indeed, CK2 inhibition with DRB leads to increased TRAIL-induced apoptosis in colon carcinoma cells, correlating with increased TRAIL-induced death-inducing signaling complex (DISC) formation, caspase-8 cleavage, and Bid cleavage, leading to proapoptotic factor release from the mitochondria." (PMID 28134850, 2017). "Inhibition of caspase-8 almost completely reversed the apoptotic levels of SW1116, SW480 and DLD-1 cells after TSLP stimulation at 100 ng/ml to the baseline levels, and significantly decreased apoptosis of colon cancer cells after TSLP stimulation at 200 ng/ml." (PMID 26919238, 2016). "However, no significant changes on caspase-8 were observed in LoVo colon cancer cells." (PMID 25342273, 2014). "Although caspase-8 was activated during the DRE exposure, it was not required for the progression of apoptosis in colon cancer cells, as the caspase-8 specific inhibitor, IETD-fmk, did not change the DRE response in these cells." (PMID 27564258, 2016). "Ezrin phosphorylation on threonine 567, although reported as a prerequisite for Fas aggregation and caspase-8 activation, did not enhance Fas ligand- nor TRAIL-induced cell death in colon cancer cells." (PMID 26010871, 2015). "However, treatment with MM131 resulted in the activation of caspase-8 in HT-29 colon cancer cells, but the effect was not so significant like in DLD-1 colon cancer cells." (PMID 33918514, 2021). "Like THP1 macrophages, normal peripheral blood monocytes restored the MMP and prevented activation of caspase 8 and cleavage of PARP in TRAIL-treated tumor cells (data not shown), which is consistent with the ability of colon cancer cells to induce IL-1β release from peripheral blood monocytes." (PMID 20661477, 2010).
melanoma (106 papers, 2002 to 2026). A malignant, usually aggressive tumor composed of atypical, neoplastic melanocytes. "Collectively these results suggest a shared common causal variant between melanoma risk and melanocyte-specific cis-regulation of CASP8." (PMID 41542517, 2026). "TWAS of melanoma risk using mammary and skin tissues found both CASP8 and FLACC1 to be significant TWAS genes with the same direction of effect observed in melanocytes." (PMID 41542517, 2026). "In melanoma cultures, the rs10931936 risk-T allele is marginally associated with multiple transcripts, including CASP8 (P = 0.07)." (PMID 41542517, 2026). "Both TWAS and colocalization approaches suggest that melanoma risk and melanocyte eQTL for CASP8 likely share one or more common causal variant, with colocalization strongly nominating rs3769823." (PMID 41542517, 2026). "Among the genes we identified, many are known melanoma susceptibility genes including CASP8, ARNT, and OCA2 (downregulated), PARP1, SETDB1, MTAP, SLC45A2, and MC1R (upregulated), and MX2 (both up‐ and downregulated)." (PMID 38308491, 2024). "Intrinsic resistance to TRAIL has been linked to the downregulation of caspase-8 through the hypermethylation of its promoter in Ewing tumor although this is still to be seen in melanoma." (PMID 34299249, 2021). "Previous studies from our group have demonstrated that combination treatment with bortezomib and IFN-α synergistically enhances melanoma apoptotic cell death through the Fas Associated Death Domain (FADD)-induced caspase-8 activation." (PMID 27783987, 2016). "Treatment of SK-MEL-2 melanoma cells with TPL at various doses for 24 h caused activations of caspase-8, -9, and -3 and TPL-induced FAK cleavage during apoptosis." (PMID 25945102, 2013). "Recently, it has been reported that deficiency in caspase-8 expression was a key determinant of apoptosis sensitivity of malignant brain tumours and melanoma." (PMID 14583775, 2003). "A number of recent studies have investigated the expression of these proteins in various types of tumour cells and reported differences, for instance loss of caspase-8-expression in a number of neuroblastomas and of Apaf-1 in melanomas." (PMID 11953820, 2002). "Several fine-mapped melanoma risk variants at this locus are clearly located within melanocyte gene-regulatory regions, including regions annotated as active promoters, consistent with a potential role for this signal regulating CASP8 levels." (PMID 41542517, 2026). "In contrast, eQTL and TWAS results in human primary melanocytes provide strong evidence suggesting cis-gene regulation as a likely mechanism underlying melanoma risk attributable to this locus, where melanoma risk-associated alleles were significantly correlated with lower levels of CASP8." (PMID 41542517, 2026). "We also examined several cell death related markers, including Bax (BCL2-associated X protein), caspase 3 (Casp3) and caspase 8 (Casp8), which confirmed that only Znpp treatment could mitigate melanoma bone metastasis-induced osteocyte death." (PMID 39814705, 2025). "A potential explanation for this observation could be the role of CASP8 in increasing NF-κB levels, an event we and others have previously linked to enhanced melanoma cell growth." (PMID 35357426, 2022). "Similarly, a previous report showed that both mitochondrial and caspase-8-dependent pathways are implicated in poly(I:C)-induced apoptosis in melanoma cells." (PMID 25227113, 2014). "Previously, it has been shown that reduced caspase-8 expression in human cancer has been frequently caused by hypermethylation of the promoter region of the gene e.g. in Ewing tumor, neuroblastoma, malignant brain tumors, rhabdomyosarcoma or melanoma cells." (PMID 24618889, 2014). "This direction matches the eQTL direction of effect for rs3769823 and CASP8 in melanocytes, melanomas, skin, and mammary tissues." (PMID 41542517, 2026).
melanoma (continued). "Both also provide some support for FLACC1, where in contrast to the CASP8 eQTL, higher FLACC1 levels are associated with the melanoma risk allele." (PMID 41542517, 2026). "This positive correlation with CASP8 in melanocytes and some melanoma tumors is inconsistent with the established role for REST as a transcriptional repressor." (PMID 41542517, 2026). "We were able to replicate this positive correlation specifically between IRF2 and CASP8 in independent panels of melanoma cell lines (P = 4.23 × 10−4, r = 0.38) and the Leeds Melanoma Cohort (P = 8.74 × 10−4, r = 0.30)." (PMID 41542517, 2026). "This direction of effect is consistent with a potential role for IRF2 as a potential activator in both individual and haplotype-based reporter assays, but inconsistent with the direction of the relatively weak eQTL for CASP8 in melanoma tumors." (PMID 41542517, 2026). "Researchers observed apoptosis associated with the activation of caspase-3, caspase-7, caspase-8 and caspase-9, as well as cleavage of BID and PARP, which is similar to our results of MZB activity against melanoma cells." (PMID 39057424, 2024). "Reducing cell adhesion and transendothelial migration; induction of apoptosis via caspase-8 and -9 activation; enhancement of methotrexate’s antiproliferative effects in melanoma cells, sparing human epidermal melanocytes." (PMID 39594665, 2024). "The overexpression of ING4 can inhibit melanoma growth and induce apoptosis through the mitochondrial pathway by increasing Fas expression, which activates caspase-8." (PMID 39329914, 2024). "Using melanoma as a cancer model, the authors demonstrate Caspase-8 can influence cell cycle progression upon DNA damage." (PMID 37444381, 2023). "In B16F10 mouse melanoma cells, high-dose ascorbate led to the induction of caspase-8-independent apoptosis via decrease in transferrin receptor-dependent cellular iron uptake." (PMID 36672190, 2023). "Recent findings have shown that only EDA-unbound cell membrane EDAR in melanoma cells exerts a proapoptotic action by recruiting Caspase-8." (PMID 37430358, 2023). "Three genes of the final associative network, CASP8, ATM, and PARP1, are associated in GWAS with melanoma as an example of positive associations of cancer with neurodegenerative disorders characterizing different molecular pathophysiology." (PMID 37298337, 2023). "The clinical data from TCGA and ICB-treated datasets revealed that in certain cancer types, especially melanoma, Casp8 plays a pro-inflammatory role." (PMID 36635765, 2023). "Caspase-9 dominated in A375 melanoma cells, while caspase-8 was mainly activated in the C32 cell line." (PMID 35055021, 2022). "We followed up on this observation and report here that overexpression of Usp27x in human melanoma cells leads to loss of the cFLIPL protein and sensitizes to TNF and pIC induced apoptosis through enhanced processing of caspase-8." (PMID 35044632, 2022). "We also identified that conditional knockout of Casp8 in NK cells caused a reduction in IFN‐γ and CD107a secretion and an increase in PD‐1 and CTLA‐4 expression, thereby promoting tumor growth of melanoma cells in Ncr1iCre/+Casp8fl/fl mice." (PMID 33934451, 2021). "Melanoma cells with Casp8 knocked down exhibited sensitivity to anti‐PD‐1 or anti‐CTLA‐4 antibody treatments, particularly in Ncr1iCre/+Casp8fl/fl mice." (PMID 33934451, 2021). "From in vitro experiments of hispidulin against melanoma, it was found that hispidulin effectively activates caspase 8 and caspase 9, as well as increases the expression of cleaved caspase 3 and cleaved PARP." (PMID 34356663, 2021).
melanoma (continued). "Here, we found that knocking down Casp8 in mouse melanoma cells promoted tumor progression in an immune system–dependent manner." (PMID 33934451, 2021). "In many tumors with poor prognosis, such as hepatocellular carcinoma, cervical cancer, and melanoma, caspase-8 was found in high levels within the nucleus." (PMID 33026575, 2021). "Further studies will reveal the role of TP-472 in activating caspase 8/9-independent apoptotic pathways in melanoma cells." (PMID 34771678, 2021). "After treating melanoma cells with rCTII, the ratio of caspase-8/caspase-9 was 2.513, highlighting the dominance of the intrinsic pathway of apoptosis." (PMID 33167431, 2020). "Treatment of melanoma cells with specific caspase inhibitors demonstrated that IRAK-M-induced cell death occurred in a caspase-3-dependent but caspase-8- and −9-independent fashion." (PMID 32533049, 2020). "The qRT-PCR was performed to evaluate the expression levels of matrix metallopeptidase 3 (MMP-3), SMAD2, SMAD3, caspase-8, caspase-9, and miR-214 in order to reveal the rCTII-induced signaling pathways in melanoma." (PMID 33167431, 2020). "Inhibition of caspase-8 also significantly reduced total ubiquitination after treatment with TRAIL in A375 melanoma cells." (PMID 31645897, 2019). "Increased levels of Fas, cleaved caspase-8, and caspase-3, and decreased levels of FasL and procyclic acidic repetitive protein are all observed in melanoma, demonstrating that ING4 achieves functionality via the Fas/Caspase-8 pathway." (PMID 30643005, 2019). "Studies have shown that apoptosis induced by HVJ-E infection is associated with the activation of caspase-8 in PC3 human prostate cancer cells and the activation of caspase-9 in murine B16F10 melanoma cells." (PMID 30534001, 2018). "Quite a few studies have reported the role of caspase-8 in the apoptotic mechanism of various cell types, such as melanoma A375 cells, neutrophils and head and neck carcinoma cells (27, –29)." (PMID 28177059, 2017). "The results also included 10 SNPs previously identified for melanoma risk reported at MC1R (2 SNPs), MX2, TERT/CLPTM1L, PLA2G6, CASP8, ACTRT3, ASIP, CDC91L1, and ARNT/SETDB1/LASS2ANXA9/MCL1/CTSK." (PMID 27993549, 2017). "Our group has previously shown a similar pattern of caspase activation and cleavage of PARP with bortezomib in human melanoma cell lines which demonstrated bortezomib-induced apoptosis as a result of FADD-induced caspase-8 activation." (PMID 27783987, 2016). "Taken together, our observations suggest that p-PD mediates apoptotic destruction of human and mouse melanoma cells primarily via the loss of MMP, activation of caspase 8, and ROS generation." (PMID 27293892, 2016). "Data of Chawla-Sarkar and colleagues provided evidence that IFN-β induced apoptosis in WM9 melanoma cells in a caspase-8 dependent manner via induction of an autocrine/paracrine TRAIL feedback loop." (PMID 26863029, 2016). "Recently, it has been shown that TIMP-3, a potent inducer of apoptosis, promotes death in melanoma cells through the stabilization of death receptors and consequent activation of their apoptotic-signaling cascade through caspase-8." (PMID 26291714, 2015). "Vitamin C is generally known to have anti-oxidant activity, but contrary to expectations, its anti-cancer activity in melanoma cells has proven to be related to oxidative stress instead, due to the caspase 8 pathway." (PMID 25102117, 2014). "Similar to adenoviral-based overexpression of TIMP3 in melanoma cells, overexpression of TIMP3 in Cal78 cells caused activation of caspase-8, a key mediator in death receptor-mediated signaling." (PMID 23894681, 2013). "Altogether, iz-TRAIL kills melanoma cells by activating the extrinsic apoptosis pathway involving caspase-8, -3 and PARP cleavage." (PMID 20461078, 2010). "Collectively, these data suggest that the melanoma GWAS signal may be explained by cis-regulation of CASP8 and FLACC1, with opposite directions of effect for the two genes." (PMID 41542517, 2026).